PCNP (PEST proteolytic signal containing nuclear protein)
Diseases named in the same sentence as PCNP in open-access papers (continued):
Sharing a sentence is not in itself a finding about the gene and the disease.
tumor (8 papers, 2019 to 2025). "PCNP expression was closely correlated with the degree of tumor differentiation, TNM clinical stage, as well as lymph node metastasis (P < 0.05)." (PMID 36703786, 2022). "In the present study, the results showed that the expression levels of PCNP in human thyroid tissues were higher than those in adjacent non‐tumor tissues." (PMID 35813472, 2022). "HE staining results revealed that PCNP was negatively correlated to tumor malignancy and metastasis." (PMID 35813472, 2022). "The overexpression of PCNP was confirmed by immunohistochemical analysis of microarray including 91 TC specimens and adjacent non-tumor patient samples." (PMID 35813472, 2022). "A PEST containing nuclear protein (PCNP) was demonstrated as a tumor suppressor in a neuroblastoma cancer model and tumor promoter in lung adenocarcinoma cancer model." (PMID 31487123, 2019). "High expression of PCNP was specifically associated with higher tumor differentiation, lack of lymph node metastasis, and lower tumor node metastasis stage (all P < 0.05)." (PMID 36703786, 2022). "Relative to the treatment of oe-LINC00858 + sh-NC, the expression levels of RAD21 and PCNP, and phosphorylation levels of STAT3 and STAT5 in the tumor tissues were lower after treatment of oe-LINC00858 + sh-RAD21." (PMID 35468892, 2022). "When compared with the oe-LINC00858 + sh-NC treatment, the volume and weight of tumor after treatments of oe-LINC00858 + sh-RAD21 and oe-LINC00858 + sh-PCNP were lower." (PMID 35468892, 2022). "In the tumor tissues following oe-LINC00858 + sh-PCNP treatment, RAD21 expression was not altered while PCNP expression and phosphorylation levels of STAT3 and STAT5 were decreased in those following oe-LINC00858 + sh-NC treatment." (PMID 35468892, 2022).
adenocarcinoma (1 paper, 2022). A common cancer characterized by the presence of malignant glandular cells. "Overexpression of PCNP promoted the proliferation, migration, and invasion of adenocarcinoma cells, while knockdown of PCNP exhibited the opposite effects." (PMID 35186732, 2022).
PCNP also shares sentences with these, for which no sentence is quoted: myeloid leukemia (4 papers); fibrosarcoma (2); central nervous system cancer (1); lung carcinoma (1); myeloma (1).